RAD51C (RAD51 paralog C)
Description:
Essential for the homologous recombination (HR) pathway of DNA repair. Involved in the homologous recombination repair (HRR) pathway of double-stranded DNA breaks arising during DNA replication or induced by DNA-damaging agents. Part of the RAD51 paralog protein complexes BCDX2 and CX3 which act at different stages of the BRCA1-BRCA2-dependent HR pathway. Upon DNA damage, BCDX2 seems to act downstream of BRCA2 recruitment and upstream of RAD51 recruitment; CX3 seems to act downstream of RAD51 recruitment; both complexes bind predominantly to the intersection of the four duplex arms of the Holliday junction (HJ) and to junction of replication forks. The BCDX2 complex was originally reported to bind single-stranded DNA, single-stranded gaps in duplex DNA and specifically to nicks in duplex DNA. The BCDX2 subcomplex RAD51B:RAD51C exhibits single-stranded DNA-dependent ATPase activity suggesting an involvement in early stages of the HR pathway. Involved in RAD51 foci formation in response to DNA damage suggesting an involvement in early stages of HR probably in the invasion step. Has an early function in DNA repair in facilitating phosphorylation of the checkpoint kinase CHEK2 and thereby transduction of the damage signal, leading to cell cycle arrest and HR activation. Participates in branch migration and HJ resolution and thus is important for processing HR intermediates late in the DNA repair process; the function may be linked to the CX3 complex. Part of a PALB2-scaffolded HR complex containing BRCA2 and which is thought to play a role in DNA repair by HR. Protects RAD51 from ubiquitin-mediated degradation that is enhanced following DNA damage. Plays a role in regulating mitochondrial DNA copy number under conditions of oxidative stress in the presence of RAD51 and XRCC3. Contributes to DNA cross-link resistance, sister chromatid cohesion and genomic stability. Involved in maintaining centrosome number in mitosis.
Synonyms: R51H3; RAD51L2; FANCO; BROVCA3
Tractability: Small molecule: a structure with a bound ligand is known. PROTAC: ubiquitination databases record sites on it.
Gene: Protein-coding gene on chromosome 17 (58,692,573 to 58,735,611, forward strand). Ensembl gene ENSG00000108384.
Subcellular location: Nucleus; Cytoplasm; Cytoplasm, perinuclear region; Mitochondrion
Subcellular location (Human Protein Atlas): Cytosol; Mitochondria; Nucleoplasm; Cell Junctions; Vesicles
Pathways (Reactome):
DNA Repair: HDR through Homologous Recombination (HRR); Homologous DNA Pairing and Strand Exchange; Presynaptic phase of homologous DNA pairing and strand exchange; Resolution of D-loop Structures through Holliday Junction Intermediates; Resolution of D-loop Structures through Synthesis-Dependent Strand Annealing (SDSA)
Disease: Defective HDR through Homologous Recombination Repair (HRR) due to PALB2 loss of BRCA1 binding function; Defective HDR through Homologous Recombination Repair (HRR) due to PALB2 loss of BRCA2/RAD51/RAD51C binding function; Defective homologous recombination repair (HRR) due to BRCA1 loss of function; Impaired BRCA2 binding to PALB2
Hemostasis: Factors involved in megakaryocyte development and platelet production
Reproduction: Meiotic recombination
Gene Ontology:
Molecular function: crossover junction DNA endonuclease activity; four-way junction DNA binding; protein binding; DNA binding; ATP binding; ATP-dependent DNA damage sensor activity
Biological process: DNA recombination; DNA repair; double-strand break repair via homologous recombination; positive regulation of G2/M transition of mitotic cell cycle; replication fork processing; supramolecular fiber organization; meiotic DNA recombinase assembly; sister chromatid cohesion; telomere maintenance via recombination
Cellular component: cytoplasm; cytosol; mitochondrion; nuclear replication fork; nucleoplasm; nucleus; perinuclear region of cytoplasm; Rad51B-Rad51C-Rad51D-XRCC2 complex; Rad51C-XRCC3 complex; replication fork
Genetic constraint (gnomAD): Loss-of-function variants: 42 observed, 47.69 expected, observed/expected ratio (o/e) 0.88, 90% interval 0.69 to 1.14. The upper end of that interval is the gene's LOEUF score, 1.14, which puts it in group 4 of 6, group 1 being the genes least tolerant of losing a copy. Missense variants: 474 observed, 475.56 expected, observed/expected ratio (o/e) 1, 90% interval 0.92 to 1.08. Synonymous variants: 172 observed, 170.21 expected, observed/expected ratio (o/e) 1.01, 90% interval 0.89 to 1.15.
Gene-disease validity (ClinGen):
ClinGen rates the evidence that RAD51C causes each of these diseases.
RAD51C-related cancer predisposition (autosomal dominant): Definitive. Hereditary cancer predisposition due to variation(s) in the RAD51C gene.
Fanconi anemia complementation group O (autosomal recessive): Limited.
Cancer hallmarks: cell replicative immortality (promotes); genome instability and mutations (suppresses)
Homologues: Orthologues: chimpanzee RAD51C (99% identical), macaque RAD51C (96% identical), dog RAD51C (90% identical), pig RAD51C (88% identical), guinea pig RAD51C (86% identical), rat Rad51c (85% identical), mouse Rad51c (84% identical), tropical clawed frog rad51c (60% identical), zebrafish rad51c (57% identical), Drosophila melanogaster spn-D (22% identical). Paralogues in human: RAD51B (26% identical), RAD51 (25% identical), DMC1 (25% identical), XRCC3 (23% identical), RAD51D (20% identical), XRCC2 (16% identical).
Diseases named in the same sentence as RAD51C in open-access papers:
RAD51C is named in the same sentence as 115 diseases in open-access papers, as found by Europe PMC text mining. Sharing a sentence is not in itself a finding about the gene and the disease. The quoted sentences say what the papers report.
ovarian carcinoma (202 papers, 2011 to 2026). A malignant neoplasm originating from the surface ovarian epithelium. "At present, no robust evidence supports an association between pathogenic RAD51C variants and an increased risk for malignancies other than breast or ovarian cancer." (PMID 41528496, 2026). "Individuals who carry RAD51C or RAD51D mutations have a significantly higher risk of developing breast or ovarian cancers than the general population." (PMID 39202057, 2024). "In our local high-risk Chinese breast and ovarian cancer cohort, RAD51C and RAD51D mutation percentages were 0.13% and 0.35%." (PMID 39202057, 2024). "Among ovarian cancer patients, RAD51C/D mutation carriers presented with a higher stage of ovarian cancer at diagnosis (p-value = 0.0117)." (PMID 39202057, 2024). "What is the prevalence of homologous recombination deficiency (HRD) in tumors from patients with germline RAD51C/D breast and ovarian cancer?" (PMID 38648056, 2024). "Studies on unselected breast or ovarian cancer cohorts in different populations showed that mutation frequencies of RAD51C and RAD51D in BC patients ranged from 0.07% to 0.2% and 0.07% to 0.48%, respectively." (PMID 39202057, 2024). "The frequency of RAD51C mutations was 0.41% (14/3429) in epithelial ovarian cancer (EOC) cases in a large case-control study." (PMID 38360632, 2024). "Germline mutations in breast and ovarian cancer pedigrees have established RAD51C as a human cancer susceptibility gene." (PMID 38360632, 2024). "RAD51C, a newly identified gene highly associated with breast and ovarian cancer, is involved in the DNA double-strand break repair pathway and plays an important role in DNA damage response." (PMID 37074454, 2023). "RAD51C mutations have previously been reported to increase the risk for breast and ovarian cancer and to also be causative for a recessively inherited Fanconi anemia-like disorder, similar to BRCA1, BRCA2 and PALB2 mutations." (PMID 37578974, 2023). "Through modified segregation analysis including families from this study, risk estimates for breast and ovarian cancer have been refined for PTVs in RAD51C, RAD51D, PALB2 and for the moderate penetrance missense variant BRCA1 c." (PMID 37563628, 2023). "The currently identified RAD51C duplication was confirmed as the same chr17 c.-31512_965+1210dup{insCTTTTGTGAG} allele that has previously been reported in breast and ovarian cancer cases from a Southern Finnish cohort (6/2533, 0.2%)." (PMID 37578974, 2023). "Of the previously established breast and/or ovarian cancer susceptibility genes, only RAD51C had a CNV alteration." (PMID 37578974, 2023). "The association between RAD51C/D pathogenic mutations and ovarian cancer has already been established in several studies." (PMID 37444530, 2023). "The relative risk caused by RAD51C mutations has been estimated higher for ovarian cancer (risk ratio 7.55) than it is for breast cancer (risk ratio 1.99), which places RAD51C in the category of moderate-risk genes." (PMID 37578974, 2023). "Loss-of-function variants of the RAD51C gene are known to confer a risk of breast and ovarian cancers." (PMID 35740625, 2022). "Based on the studies in breast and ovarian cancer, BRCAness are present in about 20% of breast cancer and 45% of ovarian cancer, such as the mutations in RAD51C, NBS1, BRIP1, and PALB2." (PMID 36497135, 2022). "While protein-truncating variants in RAD51C have been shown to predispose to triple-negative (TN) breast cancer (BC) and ovarian cancer, little is known about the pathogenicity of missense (MS) variants." (PMID 35039523, 2022). "Along with defects in BRCA1 and BRCA2, other genes that function in homologous recombination repair (HRR) are mutated in ovarian cancer, albeit at lower frequencies, including RAD51C, RAD51D, BRIP1, PALB2, and ATM." (PMID 35223797, 2022).
ovarian carcinoma (continued). "Monoallelic pathogenic variants in FANCD1/BRCA2, FANCS/BRCA1, FANCJ/BRIP1, FANCM, FANCN/PALB2, and FANCO/RAD51C have been linked to familial breast and ovarian cancer." (PMID 36428697, 2022). "Promoter silencing of the HR genes, including BRCA1 and RAD51C, has been detected in ovarian cancers associated with HRD phenotypes, and this is one of the major causes of gene inactivation." (PMID 35626108, 2022). "RAD51C loss-of-function variants are associated with an increased risk of breast and ovarian cancers." (PMID 35740625, 2022). "Germline mutations impairing RAD51C functions are susceptibility factors for breast and ovarian cancers like BRCA1/235." (PMID 36319719, 2022). "We found that a pathogenic mutation in BRCA1, BRCA2, RAD51C or PALB2 was found in 12.51% of unselected cases of ovarian cancer in Poland." (PMID 33670479, 2021). "One of 3 mutations in RAD51C was seen in 15 out of 2095 (0.72%) ovarian cancer cases and in 2 out of 1743 controls (0.11%) (OR = 6.28; 95% CI 1.77–39.9; p = 0.02)." (PMID 33670479, 2021). "In Poland, founder mutations in BRCA1, BRCA2, PALB2, CHEK2, and RAD51C have been associated with familial breast and ovarian cancer." (PMID 33670479, 2021). "The importance of the RAD51 paralogs was further underlined by genetic studies showing an increased risk of developing breast and/or ovarian cancer in women bearing RAD51C, RAD51D or XRCC2 mutations." (PMID 34208195, 2021). "RAD51C has been recently shown to confer moderate risk for breast (relative risk (RR) = 1.99, 95% CI: 1.39–2.85) and high risk for ovarian cancers (RR = 7.55, 95% CI: 5.6–10.19); however, there have only been observational studies so far for EC." (PMID 33917078, 2021). "Mutations in the RAD51C gene were reported to predispose to ovarian cancer, as well as to breast cancer but only in families with ovarian cancer cases." (PMID 33670479, 2021). "In our study one of three tested recurrent RAD51C germline mutations was detected in 15 out of 2095 (0.72%) unselected ovarian cancer patients giving the odds ratio of 6.28 (95% CI: 1.77–39.87; p = 0.02)." (PMID 33670479, 2021). "In the meta-analysis encompassing approximately 24,000 ovarian cancer patients from 53 studies and more than 100,000 controls, mutations in RAD51C were associated with a 5-fold elevated risk of ovarian cancer (OR = 5.59; 95%CI: 4.42–7.07; p < 0.0001)." (PMID 33670479, 2021). "Among the four cases of patients with ovarian cancer, we found a Pathogenic variant in RAD51C, 2 VUSs, respectively in ATM and RAD50 genes, and a Likely-benign variant in STK11." (PMID 34299313, 2021). "A biallelic RAD51C point mutation in residue R258H was found in a patient who exhibited FA-like symptoms, while monoallelic mutations in RAD51C are observed in hereditary breast and ovarian cancers." (PMID 33015624, 2020). "The cumulative risk of having ovarian cancer by age 80 was estimated to be 11% (95% CI 6–21%) for RAD51C and 13% (95% CI 7–23%) for RAD51D based on their segregation analysis." (PMID 33086730, 2020). "Invasive ductal breast carcinoma and HGSC represent the most common histotypes for RAD51C‐associated breast and ovarian cancer respectively." (PMID 31782267, 2020). "Based on the latest National Comprehensive Cancer Network Guideline, PALB2 is categorized as a gene associated with breast cancer risk, whereas BRIP1 and RAD51C are categorized as genes associated with ovarian cancer risk." (PMID 32269964, 2020). "Monoallelic mutations in five of these genes (BRCA1, BRCA2, PALB2, BRIP1 and RAD51C) increase the susceptibility to breast/ovarian cancer and are used in clinical diagnostics as bona-fide hereditary cancer genes." (PMID 32235514, 2020). "In ovarian cancer, monoallelic RAD51C and RAD51D mutations are primarily germline, although somatic mutations have also been identified." (PMID 33015624, 2020).
ovarian carcinoma (continued). "There are many studies showing the presence of mutant RAD51C mutations in breast cancer and/or ovarian cancer families, indicating RAD51C as a cancer-predisposing gene." (PMID 30975222, 2019). "It has been estimated that 3% of hereditary ovarian cancer patients have a mutation in RAD51C, whereas 5% have a mutation in RAD51D." (PMID 30551670, 2018). "Epigenetic silencing of RAD51C has been described in ovarian cancer with BRCA1 deficiency but not in TGCTs." (PMID 29898407, 2018). "Other members of the FANCG complementation group include breast and ovarian cancer associated genes; FANCO (RAD51C), FANCS (BRCA1), BRCA2 (FANCD1), BRIP1 (FANCJ) and PALB2 (FANCN)." (PMID 28591191, 2017). "Since Rad51 depletion enhances type I IFN signalling in vitro, we examined patients with breast or ovarian cancer due to RAD51C mutation for signs of autoimmunity." (PMID 27230542, 2016). "Mutations in HR genes such as BRCA1, BRCA2, or RAD51C predispose individuals to breast and ovarian cancers." (PMID 26748828, 2016). "We have previously identified Finnish founder mutations in the ovarian cancer susceptibility genes RAD51C and RAD51D and recently, we identified a recurrent nonsense mutation in the FANCM gene that associated especially with triple-negative breast cancer." (PMID 25918678, 2015). "Again, this illustrates the potential of WGS and multi-gene panels to identify co-occurring cancer gene mutations (e.g. RAD51C and FH) that pose genetic risks (breast/ovarian cancer) beyond the patient's primary diagnosis (leiomyoma)." (PMID 26023681, 2015). "The RAD51C c.706-2A > G mutation co-segregated with an ovarian cancer at the age of 67 years for a paternal aunt of the index case." (PMID 24139550, 2013). "These two RAD51C mutations were detected in families with both breast and ovarian cancer cases, which is consistent with previous studies." (PMID 24139550, 2013). "Mono-allelic germline mutations conferring breast and ovarian cancer predisposition were identified in RAD51C and RAD51D." (PMID 24139550, 2013). "As with BRCA2/FancD1, BRIP1/FancJ, and PALB2/FancN, bi-allelic mutations in RAD51C/FancO cause FA, and mono-allelic mutations increase the risk of breast and ovarian cancer." (PMID 23344037, 2013). "Following more recent discoveries of susceptibility genes for ovarian cancer, the molecular diagnosis of ovarian cancer predisposition within risk families was extended to novel genes such as RAD51C." (PMID 23344037, 2013). "Current data from The Cancer Genome Atlas (TCGA) shows that the frequency of heterozygous loss of HELQ in ovarian cancer is comparable to RAD51C and RAD51D." (PMID 24005565, 2013). "Recent studies conducted on RAD51 paralogs, involved in the same DNA repair pathway, have identified rare germline mutations conferring breast and/or ovarian cancer predisposition in the RAD51C, RAD51D and XRCC2 genes." (PMID 24139550, 2013). "RAD51C was investigated as a possible breast and ovarian cancer susceptibility gene in 1100 high-risk families, who were previously tested negative for BRCA1 and BRCA2 mutations." (PMID 23586058, 2013). "Rare, heterozygous germline mutations in the RAD51C gene have been found in breast and ovarian cancer families." (PMID 23176254, 2012). "In RAD51C, heterozygous germline mutations have been identified in breast and ovarian cancer families and a homozygous missense mutation was found in a Fanconi anemia like disorder." (PMID 23176254, 2012). "Our results provide further data that RAD51C is a predisposition gene for hereditary breast and ovarian cancers." (PMID 21980511, 2011). "RAD51C mutations appear to be rare mutations that predispose to ovarian cancer, as well as to breast cancer but only in families with ovarian cancer." (PMID 21980511, 2011). "Notably, the cumulative risk of ovarian cancer among women with pathogenic RAD51C variants was reported to be 1% by age 50, but to increase substantially thereafter, with a peak at 60–69 years of age." (PMID 41528496, 2026).